IL1B (interleukin 1 beta)
Diseases named in the same sentence as IL1B in open-access papers (continued):
Sharing a sentence is not in itself a finding about the gene and the disease.
periodontitis (continued). "In the present study, we generated Synoviolin conditional KO mice and found that these mice produced more mature IL‐1β and IL‐18 and had exacerbated periodontitis, suggesting that Synoviolin played a protective role in periodontitis by suppressing inflammasome activation." (PMID 37506160, 2023). "In addition, inflammatory factors of periodontitis, such as IL-1β, IL-6, IL-8, and TNF-α also significantly reduced in the Fn+AKK group." (PMID 37460552, 2023). "Our results showed that the presence of SB significantly inhibited inflammatory cell infiltration and prevented the increase of the relative mRNA expression of TNF-α, IL-1β, and IL-6 in both in vivo and in vitro models, which indicates that SB effectively inhibited the inflammation in periodontitis." (PMID 36846719, 2023). "IL-1β production is closely related to the pathogenesis of periodontitis." (PMID 37626627, 2023). "However, in this study, we further explored the causal effects of periodontitis-related phenotypes, including PCT3, PCT5 and inflammatory indicators IL-1β on COVID-19, and obtained the causal association of IL-1β in gingival crevicular fluid on COVID-19." (PMID 36718446, 2023). "Therefore, it is likely that these immune cell-derived cytokines such as Tnfα and IL-1β in chronic periodontitis conditions induce matrix breakdown in the connective tissues." (PMID 38156070, 2023). "The level of IL-1β has great monitoring value in predicting the progression of periodontitis." (PMID 36726081, 2023). "Some of them, such as IL-1β and IL-6, in saliva could be candidates for early diagnosis of periodontitis." (PMID 36983201, 2023). "Ligature-induced periodontitis significantly increased periodontal bone loss in 3 × Tg-AD, which was accompanied by increased total bacterial load and elevated gene expression levels of MCP-1, TNF-α and IL-1β in the gums." (PMID 36915108, 2023). "In P. gingivalis-associated ligature-induced experimental periodontitis, the adoptive transfer of Breg cells (CD1dhiCD5+) induced a gingival decrease in the production of RANKL, TNF-α, and IL-1β and an increase in the production of IL-10, which inhibited periodontal bone loss." (PMID 37217496, 2023). "Hence, this study compared the benefits of using tetracyclines and probiotics as LDDs after SRP on clinical parameters and IL1β levels in diabetic patients with periodontitis." (PMID 38249256, 2023). "Moreover, by means of Spearman’s correlation, we observed that the patients with grade C periodontitis exhibited a moderate to strong positive correlation between IL-1β and the clinical parameters PPD (r = 0.493; p < 0.05) and CAL (r = 0.743; p < 0.01)." (PMID 36769650, 2023). "We discovered 3 periodontitis-associated genes (CASP3, IL-1β, and TXN)." (PMID 37475857, 2023). "However, treatment with FK506/EPO effectively suppressed the increase in serum TNF-α, IL-1β, and IL-6 induced by experimental periodontitis." (PMID 38239915, 2023). "Furthermore, the IL‐1β level in the serum of patients with severe periodontitis was significantly higher than in the serum of patients with mild periodontitis." (PMID 37506160, 2023). "In addition, the IL‐1β/IL‐10 ratio and TNF‐α/IL‐4 ratio in the biopsies of periodontitis patients are strongly associated with the severity of periodontitis." (PMID 37647428, 2023). "Periodontitis pathogens can stimulate cells to produce inflammatory factors such as IL-1β, IL-6, and TNF-α and enter the body circulation system through the broken gingival epithelium in periodontal pockets, causing bacteremia, or ectopic colonization in other organs." (PMID 37808891, 2023). "Similarly, chitosan hydrogels loaded with DPSC-derived CEVs (DPSC-EVs) reduced the expression of IL-23, IL-1α, TNF-α, IL-12, IL-1β, IL-27, and IL-17 in periodontitis tissues." (PMID 36982864, 2023).
periodontitis (continued). "Higher systemic circulating inflammatory burden of CVD risks such as interleukin (IL)-1β, IL-8, IL-6 and tumor necrosis factor-alpha (TNF-α) are directly associated with the periodontitis incipient lesions in adolescents and established periodontitis in adults." (PMID 37711554, 2023). "Additionally, P. gingivalis promotes pathogenesis of aggressive periodontitis by inducing the production of proinflammatory cytokines, such as IL-1β and IL-6, from peripheral T helper cells." (PMID 38149100, 2023). "Unstimulated whole saliva (UWS) is a complex biologic fluid that expresses raised levels of proinflammatory cytokines such as interleukin 1 beta (IL-1β) under periodontal and peri-implant inflammatory conditions such as periodontitis and peri-implant mucositis and peri-implantitis, respectively." (PMID 37217913, 2023). "Furthermore, periodontitis worsens systemic inflammation, leading to the release of pro-inflammatory cytokines and tissue-damaging agents into the circulatory system, such as IL-1β, IL-10, IL-17, Th17, IFN-gamma, GM-CSF, G-CSF, IL-8, TNF-α, and MCP1." (PMID 37892006, 2023). "Increased IL-1β triggers inflammation and promotes bone resorption in periodontitis." (PMID 37090158, 2023). "Furthermore, in all severities of periodontitis, IL-1β levels in gingival sulcus fluid were more significant than in the control group and are thus considered a disease characteristic of periodontitis." (PMID 37475857, 2023). "In unstimulated whole saliva, the IL-1β levels were higher in periodontitis patients compared to healthy individuals, and severe cases presented higher values of IL-1β than moderate or initial periodontitis patients, even if applied to a low sample study." (PMID 36769650, 2023). "In addition, salivary IL-1β has proven to distinguish systemically healthy patients with untreated periodontitis from periodontally healthy ones, although this discriminatory potential was reduced in smokers." (PMID 36769650, 2023). "Similarly, we noticed that the grade C periodontitis patients presented mean IL-1β values higher than those of the grade B and grade A patients, albeit without reaching statistical significance." (PMID 36769650, 2023). "In addition, TNF‐α and IL‐1β stimulate NO expression, which enhances the progression of periodontitis." (PMID 36894516, 2023). "In periodontitis, the expression of inflammatory cytokines, such as interleukin-1 beta (IL-1β), interleukin-6 (IL-6), and tumor necrosis factor-alpha (TNF-a), is increased, and it is closely related to the destruction of periodontal tissue and alveolar bone loss." (PMID 37240020, 2023). "The results of this study and the reports from the literature indicate that the upregulated IL1β in neutrophils infiltrated in periodontal tissue during periodontitis might play a role in pyroptosis and necroptosis of surrounding tissues." (PMID 36686646, 2022). "In tissue sections, immunohistochemical staining was conducted to reveal inflammatory cytokines (IL-1β and IL-6) in the periodontal tissues of mice, which showed significant reductions of positive rates under Rd treatments, compared with the periodontitis group (p < 0.05)." (PMID 35480231, 2022). "Il-1β (23.43% ± 8.01%) and IL-6 (30.43% ± 7.39%) positive cells were partially reduced in the positive area of the IL-1ra group compared to the periodontitis group of diabetic rats, but the proportion of positive cells was still much higher than that of the blank control and periodontitis groups." (PMID 36430410, 2022). "Our findings of higher IL-1β concentrations in saliva from patients with grade B and C periodontitis are in agreement with several earlier studies that showed higher salivary levels of this analyte in patients suffering from periodontitis in comparison with healthy subjects." (PMID 35368315, 2022).
periodontitis (continued). "The proportion of Il-1β (35.11% ± 4.53%, p < 0.0001) and IL-6 (41.02% ± 10.51%, p < 0.0001) positive areas and positive cells in untreated diabetic rats with periodontitis were significantly higher than those in untreated diabetic rats with periodontitis." (PMID 36430410, 2022). "Furthermore, it was observed that IL-1β was higher in GCF compared to IL-9 levels in moderate periodontitis sites." (PMID 35270581, 2022). "In addition, the oral administration of lycopene has been shown to suppress IL1β levels in saliva and thereby periodontitis." (PMID 36501023, 2022). "Therefore, the proinflammatory cytokines TNF-α, IL-1β, and IL-6 play a key role in the occurrence and development of periodontitis." (PMID 36546940, 2022). "Therefore, the present study aimed to evaluate the unstimulated whole salivary cytokine levels of pro-inflammatory cytokine IL-1β in periodontitis patients with different severity levels." (PMID 35270581, 2022). "However, it was suggested that the distributions of IL-1B+3954 genotypes and IL-1A+4845 and IL-1B+3954 haplotypes were unique to the Japanese patients with rheumatoid arthritis and periodontitis." (PMID 36429405, 2022). "IL-1β and IL-6 concentrations were statistically higher in periodontitis patients and may be used as potential tools in periodontitis diagnosis." (PMID 35368315, 2022). "Experimental periodontitis in rats was created by elevating a full-thickness gingival flap and ligating silk threads around the mandible first molars; the expression of IL-1β was significantly decreased after 14 days of treatment with EMD when compared to control animals." (PMID 36077174, 2022). "The synergistic responses of HGFs by IL-1β and IL-6/sIL-6R may promote periodontal inflammation by inducing the expression of gp130, resulting in the progression of periodontitis." (PMID 36359741, 2022). "For example, 830-nm GaAlAs laser radiation can have some therapeutic effects on gingivitis and periodontitis associated with bacterial infectionsby the inhibition of the production as well as the expression of the prostaglandin E2 (PGE2) and interleukin-1 beta gene." (PMID 35783494, 2022). "Treatment of both healthy and periodontally diseased gingival fibroblasts with pan-HDACi or HDAC3/6i prior to P. gingivalis infection significantly reduced the induction of a subset of inflammatory mediators (CCL2, CCL5, CXCL10, IL1B, COX2 and MMP3) implicated in periodontitis." (PMID 36291079, 2022). "An analysis of IL-1A−889 and IL-1B+3953 genotype frequencies revealed that the IL-1B+3953 C/T genotype was significantly more frequent in the group with periodontitis (p = 0.016), whereas the prevalence of the IL-1B+3953 C/C genotype was significantly lower (p = 0.029)." (PMID 36429405, 2022). "IL-1β may play a central role in regulating the inflammatory cascade surrounding fibroblasts in the early stage of periodontitis." (PMID 36359741, 2022). "Furthermore, an in vivo study reported that orthodontic force up-regulated the expression of IL-1β and TNF-α in periodontitis rats and amplified bone loss." (PMID 34185172, 2022). "In a study on periodontitis, psoralen could attenuate the inflammatory response and inhibited LPS-induced IL-1β and IL-8 mRNA expression." (PMID 35656183, 2022). "Immunohistochemical staining of rat periodontal tissue sections with IL-1β and IL-6 antibody showed that, compared to the control group, there were obvious positive areas in the periodontitis group, with proportions of IL-1β-positive cells up to 9.06% ± 5.42% and IL-6 up to 20.29% ± 4.97%." (PMID 36430410, 2022). "Moreover, the IL-1β expression of periodontitis patients was higher than healthy patients, according to previous reports." (PMID 36034700, 2022). "Thus, the aim of the present study was to evaluate salivary concentrations of IL-1β, IL-6, MMP-8, and IL-10 in healthy and periodontitis patients and to assess the association between these biomarkers levels and clinical parameters in a Moroccan population." (PMID 35368315, 2022).
periodontitis (continued). "Periodontitis is a chronic systemic inflammatory disease, and neutrophils play a pivotal role in early lesions, while inflammatory cytokines (e.g., IL-1β and TNF-α) are crucial in the pathogenesis." (PMID 36275028, 2022). "Within genotyping to reveal an increased risk of immune reactivity associated with rapid progression of periodontitis, patients H1, H2, H3, H8, H9 and H10 were found to have a positive genotype within the polymorphism in the genes IL1-A (rs1800587), IL1-B (rs1143634) and IL-1RN (rs419598)." (PMID 36290432, 2022). "TNF-α and IL-1β are critical inflammatory mediators that play an important role in the interactions between PDLSCs and immune cells, which are significant in the development of periodontitis (Pan, Wang, and Chen, 2019)." (PMID 35464198, 2022). "In addition, cases of severe periodontitis showed significantly higher UWS IL-1β levels compared to initial and moderate periodontitis patients." (PMID 35270581, 2022). "UWS IL-1β levels were higher in periodontitis patients compared to healthy individuals." (PMID 35270581, 2022). "Additionally, it was discovered that knocking down lncZFY-AS1 reduced inflammatory factors TNF-α, IL-1β, and IL-6 in the periodontitis model." (PMID 35659193, 2022). "Green tea supplementation, in addition to SRP, may reduce salivary IL-1β levels in patients with chronic periodontitis for a period of 6 weeks." (PMID 35706460, 2022). "In addition, 5 ng/ml IL‐1β reflects the concentration in gingival crevicular fluid of periodontitis patients." (PMID 33386669, 2022). "Furthermore, in the present study, the levels of miR-1246 in saliva of patients with chronic periodontitis were positively correlated with the levels of IL-1β, IL-6, IL-17, and TNF-α, indicating a correlation between the two." (PMID 35942384, 2022). "Studies revealed that by causing peripheral CD4+ T helper cells to give rise to excessive amounts of pro-inflammatory cytokines, including IL-1β and IL-6, P. gingivalis could help in better understanding severe periodontitis." (PMID 36289921, 2022). "Furthermore, the dominance of double IL-1A−889 C/C and IL-1B+3953 C/C homozygotes in the group of patients with periodontitis was also significantly lower than in healthy controls." (PMID 36429405, 2022). "Collectively, these findings suggest that reduced levels of CRP, IL-6, TNFα, and IL-1β after treatment of periodontitis could restore eNOS activity and NO bioavailability, resulting in improved endothelial dysfunction." (PMID 35874771, 2022). "Similarly, another study demonstrated that Nampt induced by IL-1β treatment was overexpressed in fibroblasts of periodontitis, and further conferred a promotive effect on inflammatory reaction and alveolar bone disruption." (PMID 34967693, 2022). "Therefore, inhibiting the production of IL-1β is expected to be effective in the treatment of periodontitis." (PMID 35566047, 2022). "Two studies showed that polymorphisms in IL-1B genes aggravate periodontitis in patients with type-2 DM, and two studies showed that IL-1B genes either do not or are less likely to contribute towards the progression of periodontitis in patients with type-2 DM." (PMID 33919509, 2021). "In our study, IL-1b could differentiate gingivitis and periodontitis from the health group, but also between gingivitis and periodontitis groups themselves." (PMID 33742017, 2021). "Moreover, Z-LEVD-FMK, a caspase-4 specific inhibitor, led to inhibition of GSDMD cleavage, caspase-4 activation, and IL-1β release in a periodontitis rat model." (PMID 35008798, 2021). "B. lactis reduces levels of IL-1b and IL-1b/IL-10 ratios in rats using experimental periodontitis." (PMID 34361886, 2021). "In the case of genomic regions with known genetic factors in PD, a systematic review and meta-analysis with more than 70,000 participants describes genetic variants in genes such as IL-1A, IL-1B, IL-6, IL-10, MMP-3, and MMP-9 were significantly associated with the risk of developing periodontitis." (PMID 34776994, 2021).
periodontitis (continued). "Furthermore, macrophages obtained from periodontitis patients were stimulated with E. coli LPS and P. gingivalis LPS while the expression of caspase-4 and IL-1β was seen for the cells stimulated with E. coli LPS." (PMID 35008798, 2021). "Importantly, the increased IL-1β level in gingival crevicular fluid was significantly correlated with periodontitis severity." (PMID 33869229, 2021). "By releasing IL-1β into the tissue microenvironment, pyroptotic PDLSCs inhibited osteoblastogenesis and promoted osteoclastogenesis, which exacerbated the pathological damage of periodontitis." (PMID 33869229, 2021). "The MAPK pathway is the upstream signaling intermediate to many inflammatory cytokines such as TNF-α, IL-1β, IL-6, and prostaglandin E2, and the blockage of this pathway could be beneficial for treating inflammatory diseases like chronic periodontitis and AD." (PMID 33869630, 2021). "These AUC values were lower than the combination most effective at discriminating periodontitis subjects from healthy subjects (IL-1β, ICTP and Pg, with an AUC of 0.94), but were above acceptable AUC values of 0.75 and can potentially be used for clinical diagnosis." (PMID 34001101, 2021). "Nevertheless, during periodontitis, cytokines, such as Il-1β, IL-6 and TNF-α, are secreted in response to bacterial insult and could sustain the neuroinflammation process after passage through the blood–brain barrier." (PMID 34501984, 2021). "Similar to periodontitis, peri-implantitis exhibits higher IL-1β levels in diseased tissues, and these changes may persist despite nonsurgical therapy." (PMID 34177950, 2021). "IL-1β is a vital player in the pathogenesis and development of periodontitis." (PMID 34177950, 2021). "IL-1β is a noteworthy cytokine biomarker in periodontitis development and progression." (PMID 35046930, 2021). "As previous works proposed that IL-1β was a useful indicator for evaluating the host response during periodontitis and that human periodontal ligament cells released IL-1β under cyclic stretch, we detected the localization of IL-1β in periodontal ligament from periodontitis patients." (PMID 33869229, 2021). "In addition, the expressions of NLRP3, IL-1β, and IL-18 in gingival tissues of patients with gingivitis, invasive periodontitis, and chronic periodontitis were significantly increased." (PMID 34660289, 2021). "In addition to MMP-8, patients with severe periodontitis have been reported to have significantly higher levels of IL-1β and an elevated MMP-8/TIMP-1 molar ratio." (PMID 33916950, 2021). "Salivary interleukin (IL)-1β, matrix metalloproteinase (MMP)-8, pyridinoline cross-linked carboxyterminal telopeptide of type I collagen (ICTP) and Porphyromonas gingivalis (Pg) are related to periodontitis." (PMID 34001101, 2021). "In obese subjects with periodontitis, pro-inflammatory cytokines (Interleukin-1β (Il-1β), Interleukin-6 (Il-6), Tumor Necrosis Factor α (TNF-α)) were found in greater quantities in the blood and also in the crevicular gingival fluid compared to normo-weighted subjects with periodontitis." (PMID 33919425, 2021). "Moreover, to investigate, likewise, the mechanisms relating arterial hypertension and periodontitis, by evaluating the plasma levels of NO and IL-1β concentration in the myocardial tissue." (PMID 34635094, 2021). "The effect of IL-17 and IFN-γ on periodontal gingival tissues and alveolar bone suggests their proresorption roles for periodontitis in vivo, which might partly be explained by their stimulatory effect on IL-1β, TNF-α, and IL-6." (PMID 34395635, 2021). "While studies have been performed to identify these polymorphisms individually in each disease, none of the studies have been completed so far that have quantified and correlated NLRP3 and IL-1β SNPs in subjects with chronic periodontitis and coronary artery disease." (PMID 34501201, 2021).